MTIF3 (mitochondrial translational initiation factor 3)
Description:
IF-3 binds to the 28S ribosomal subunit and shifts the equilibrium between 55S ribosomes and their 39S and 28S subunits in favor of the free subunits, thus enhancing the availability of 28S subunits on which protein synthesis initiation begins.
Synonyms: IF-3Mt; IF3(mt); IF3mt
Tractability: Small molecule: a structure with a bound ligand is known. PROTAC: its protein half-life has been measured.
Gene: Protein-coding gene on chromosome 13 (27,435,634 to 27,450,613, reverse strand). Ensembl gene ENSG00000122033.
Subcellular location: Mitochondrion
Subcellular location (Human Protein Atlas): Mitochondria; Nucleoplasm
Pathways (Reactome):
Metabolism of proteins: Mitochondrial translation initiation
Gene Ontology:
Molecular function: protein binding; ribosomal small subunit binding; translation factor activity, RNA binding; translation initiation factor activity
Biological process: ribosome disassembly; mitochondrial translational initiation; translational initiation
Cellular component: mitochondrion
Genetic constraint (gnomAD): Loss-of-function variants: 14 observed, 21.88 expected, observed/expected ratio (o/e) 0.64, 90% interval 0.42 to 1. The upper end of that interval is the gene's LOEUF score, 1, which puts it in group 4 of 6, group 1 being the genes least tolerant of losing a copy. Missense variants: 295 observed, 340.75 expected, observed/expected ratio (o/e) 0.87, 90% interval 0.79 to 0.95. Synonymous variants: 114 observed, 118.06 expected, observed/expected ratio (o/e) 0.97, 90% interval 0.83 to 1.13.
Homologues: Orthologues: chimpanzee MTIF3 (99% identical), macaque MTIF3 (87% identical), rabbit MTIF3 (75% identical), dog MTIF3 (67% identical), pig MTIF3 (67% identical), mouse Mtif3 (64% identical), rat Mtif3 (63% identical), guinea pig MTIF3 (61% identical), tropical clawed frog mtif3 (34% identical), zebrafish mtif3 (32% identical).
Diseases named in the same sentence as MTIF3 in open-access papers:
MTIF3 is named in the same sentence as 15 diseases in open-access papers, as found by Europe PMC text mining. Sharing a sentence is not in itself a finding about the gene and the disease. The quoted sentences say what the papers report.
Obesity (4 papers, 2017 to 2023). Accumulation of substantial excess body fat. "Genetic variation at the MTIF3 (Mitochondrial Translational Initiation Factor 3) locus has been robustly associated with obesity in humans, but the functional basis behind this association is not known." (PMID 36876906, 2023). "Thus, MTIF3 mutations are associated with multiple pathological processes such as PD, obesity, and diabetes." (PMID 34277617, 2021). "Secondly, we hypothesized that MTIF3 content in human white adipocytes influences adipocyte-specific, obesity-related traits under basal and perturbed metabolic conditions." (PMID 36876906, 2023). "Interestingly, although there was no significant gene-diet interaction detected using the genetic risk score for obesity traits (BMI), the results did reveal that two genes (LRRN6C and MTIF3) for obesity traits were actually stronger for individuals consuming healthy foods." (PMID 29093760, 2017).
Diabetes (2 papers, 2021). "In addition, MTIF3 autoantibodies were found in patients with type I diabetes, indicating that MTIF3 is related to diabetes." (PMID 34277617, 2021).
Parkinson disease (2 papers, 2021 to 2024). A progressive degenerative disorder of the central nervous system characterized by loss of dopamine producing neurons in the substantia nigra and the presence of Lewy bodies in the substantia nigra and locus coeruleus. "This suggested that, similar to Parkinson’s disease, MTIF3 may trigger CAS by causing mitochondrial dysfunction." (PMID 38783263, 2024). "Changes in the function or expression of MTIF3 protein may affect mitochondrial function, ATP production, or the formation of reactive oxygen species (ROS), affecting susceptibility to Parkinson’s disease (PD) and promoting its occurrence." (PMID 34277617, 2021). "The MTIF3 gene may influence Parkinson’s disease by causing mitochondrial dysfunction." (PMID 38783263, 2024).
allergic asthma (1 paper, 2024). A asthma with a basis in a pathological type I hypersensitivity reaction. "The negative correlation between MTIF3 and the immature B cells may further aggravate the abnormal immune response, increase the inflammatory and bronchial contraction induced by the system, and promote the development of allergic asthma in children." (PMID 38783263, 2024).
allergic disease (1 paper, 2024). An immune response that occurs following re-exposure to an innocuous antigen, and that requires the presence of existing antibodies against that antigen. "Previous studies have shown that cell B cells play a key role in allergic diseases, while the decline of MTIF3 levels may affect the function and differentiation of juvenile b cells, further exacerbating the immune disorder caused by the process." (PMID 38783263, 2024).
asthma (1 paper, 2024). "In particular, the expression of MTIF3 gene affected mitochondria-related functions, which negatively affected the immune system response to asthma, mainly in the abundance of B cell naive cells." (PMID 38783263, 2024). "In addition, the expression of the MTIF3 and MRPS26 genes negatively affects the immune system’s response to asthma, impacting mitochondrial-related functions." (PMID 38783263, 2024).
cervical carcinoma (1 paper, 2015). A carcinoma arising from either the exocervical squamous epithelium or the endocervical glandular epithelium. "PDCD6 gene expression was higher in cells sensitive to L-OHP, whileexpression of PDS5B, UBL3, MTIF3,XPO4, CASC8, and GTF3A was lower.UBL3 was identified as one of seven genes that predict relapse andsurvival in early-stage cervical carcinoma patients." (PMID 26678268, 2015).
Crohn disease (1 paper, 2017). A gastrointestinal disorder characterized by chronic inflammation involving all layers of the intestinal wall, noncaseating granulomas affecting the intestinal wall and regional lymph nodes, and transmural fibrosis. "Using this OligoFlow method, we identified alterations in T-bet binding at rs11135484, in high LD with a SNP associated with Crohn’s disease and with rs1006353, the closest neighbor of which is MTIF3, associated with body mass index." (PMID 28187197, 2017).
Insulin resistance (1 paper, 2023). Increased resistance towards insulin, that is, diminished effectiveness of insulin in reducing blood glucose levels. "Further in vivo studies are therefore needed to establish any link between MTIF3 content and insulin resistance." (PMID 36876906, 2023).
MTIF3 also shares sentences with these, for which no sentence is quoted: cardiomyopathy (3 papers); type 1 diabetes (2); heart failure (1); immune disorder (1); mastitis (1); Thrombocytopenia (1).